SPEM1 (spermatid maturation 1)
Description:
Required for proper cytoplasm removal during spermatogenesis.
Synonyms: C17orf83; FLJ40081
Tractability: Antibody: UniProt predicts a signal peptide or a membrane-spanning region.
Gene: Protein-coding gene on chromosome 17 (7,420,324 to 7,421,632, forward strand). Ensembl gene ENSG00000181323.
Subcellular location: Membrane; Cytoplasm
Subcellular location (Human Protein Atlas): Golgi apparatus; Calyx
Gene Ontology:
Molecular function: protein binding
Biological process: flagellated sperm motility; sperm individualization
Cellular component: cytoplasm; membrane
Genetic constraint (gnomAD): Loss-of-function variants: 11 observed, 10.17 expected, observed/expected ratio (o/e) 1.08, 90% interval 0.68 to 1.73. The upper end of that interval is the gene's LOEUF score, 1.73, which puts it in group 6 of 6, group 1 being the genes least tolerant of losing a copy. Missense variants: 401 observed, 410.73 expected, observed/expected ratio (o/e) 0.98, 90% interval 0.9 to 1.06. Synonymous variants: 175 observed, 156.65 expected, observed/expected ratio (o/e) 1.12, 90% interval 0.99 to 1.27.
Homologues: Orthologues: chimpanzee SPEM1 (96% identical), macaque SPEM1 (90% identical), dog SPEM1 (70% identical), rabbit SPEM1 (70% identical), rat Spem1 (69% identical), mouse Spem1 (68% identical), guinea pig SPEM1 (64% identical).
Diseases named in the same sentence as SPEM1 in open-access papers:
SPEM1 is named in the same sentence as 6 diseases in open-access papers, as found by Europe PMC text mining. Sharing a sentence is not in itself a finding about the gene and the disease. The quoted sentences say what the papers report.
male infertility (8 papers, 2020 to 2024). The inability of the male to effect fertilization of an ovum after a specified period of unprotected intercourse. "Spem1 is exclusively expressed in the round and elongating spermatids, and the loss of this protein causes aberrant cytoplasm removal, sperm deformation, and male infertility." (PMID 33425888, 2020). "Triptonide appears to target junction plakoglobin and disrupts its interactions with SPEM1 during spermiogenesis, which contributed to its male infertility in mice and cynomolgus monkeys." (PMID 34758869, 2021). "A previous study revealed SPEM1’s indispensable role for the proper removal of cytoplasm in late spermiogenesis and genetic inactivation led to sperm deformation and male infertility, yet functional importance of other SPEM molecules in sperm development and male reproduction has been undefined." (PMID 38421455, 2024). "SPEM1 (Spermatid Maturation 1) and SPEM2 (SPEM Family Member 2) genes are related to spermatid maturation and flagelled sperm motility, and both are linked to reproductive disorders such as male infertility, spermatogenic failure and oligospermia." (PMID 35286314, 2022). "Lack of Spem1 in mice causes retention of cytoplasmic remnants on the head and neck region, and the retained cytoplasmic remnants obstruct the straightening and stretching of sperm head and neck, leading to sperm deformation and male infertility." (PMID 38421455, 2024). "This study demonstrated that appropriate cytoplasmic removal is a genetic regulatory process that requires Spem1, and that lack of Spem1 leads to sperm deformation together with male infertility." (PMID 37371084, 2023).
Azoospermia (2 papers, 2022 to 2023). Absence of any measurable level of sperm,whereby spermatozoa cannot be observed even after centrifugation of the semen pellet. "The testis-specific post-meiotic marker spermatid maturation 1 (SPEM1) showed a lower expression level in the testicular tissue of azoospermic men with non-obstructive azoospermia (NOA) as compared to those with obstructive azoospermia (OA)." (PMID 37174638, 2023).
SPEM1 also shares sentences with these, for which no sentence is quoted: Infertility (2 papers); Obesity (1); oligospermia (1); teratozoospermia (1).